BRAF (B-Raf proto-oncogene, serine/threonine kinase)
Diseases named in the same sentence as BRAF in open-access papers (continued):
Sharing a sentence is not in itself a finding about the gene and the disease.
melanoma (continued). "Constitutive upregulation of the MAPK pathway in BRAFV600 mutant melanoma appears to directly impact DC function as evident by partial restoration of IL-12 and TNF-α secretion upon treatment of melanoma cells with MEK or BRAF inhibition." (PMID 24194739, 2013). "We report here that although cotreatment with HDAC and BRAF inhibitors activates the caspase cascade and the mitochondrial apoptotic signaling, it kills BRAFV600E melanoma cells predominantly by induction of necrosis in a RIPK1- and RIPK3-independent manner." (PMID 23744355, 2013). "In contrast, differentiated melanoma cells were efficiently killed by PD0325901, regardless BRAF status." (PMID 24238212, 2013). "Further studies are warranted to confirm a potential predictive and prognostic role of BRAF and NRAS expression levels in advanced melanomas." (PMID 23673558, 2013). "Importantly, we found that Mek inhibition in vivo determined a dramatic antitumor activity both in mutated- and wild type-BRAF tumors, suggesting that MEK inhibition, by different agents, might represent a powerful and safe strategy to counteract melanoma growth, thus improving patient outcome." (PMID 24238212, 2013). "Recently, the first combined clinical trial, using BRAF and MEK inhibitors on 162 BRAFV600 mutant melanoma patients, announced encouraging results for progression-free survival improvements." (PMID 23704925, 2013). "In conclusion, we present data linking BRAF, as well as NRAS, mRNA expression levels to outcome in advanced melanoma." (PMID 23673558, 2013). "The MAPK pathway is an important therapeutic target in melanoma: BRAF, MEK, and combined BRAF/MEK inhibition with small molecule kinase inhibitors are successful treatment strategies in patients with BRAF mutant metastatic melanoma." (PMID 24194739, 2013). "We have shown previously that co-treatment of several melanoma cell lines with WNT3A and with a targeted BRAF-V600E inhibitor synergistically increases Wnt/β-catenin signaling and apoptosis." (PMID 24114839, 2013). "To date, only one report has published a role for PRMT5 in melanoma, in which PRMT5 was shown to modulate the ERK pathway in BRAF wild type cells." (PMID 24098663, 2013). "We investigated the interaction between genes within our 200-gene signature with the four known melanoma ‘driver’ genes (i.e., NRAS, BRAF, MITF and cKIT)." (PMID 23638386, 2013). "However, considering the merely cytostatic activity exerted by MEK inhibitor against wild type BRAF melanoma stem-like cells in vitro, it may be possible that MEK inhibition might kill only the differentiated cells in vivo, as well, with consequent enrichemnt of tumors in stem-like cells." (PMID 24238212, 2013). "A typical example of a genomic panel recommended for cancer diagnosis is a panel comprising of BRAF, KIT, NRAS, GNA11 and GNAQ for Melanomas." (PMID 23863689, 2013). "In another study involving melanomas, C-MYC overexpression was found to be required for the continuous suppression of BRAF(V600E) or NRAS(Q61R)-induced senescence." (PMID 24130815, 2013). "The ability of NM23 deficiency to confer metastatic potential in HGF-driven melanoma suggests the HGF+ × [m1m2]+/− strain may be a relevant experimental model for human melanomas that do not harbor BRAF mutations (20–40 %) and are unsuitable candidates for anti-BRAF therapies." (PMID 22699362, 2013). "Inhibitors of c-Kit and mitogen-activated protein kinase (MEK) have also been found to act against melanomas, and MEK inhibitors are now being examined as a strategy to overcome BRAF inhibitor resistance." (PMID 22846499, 2012). "Other molecules commonly involved in melanoma progression include NRAS and BRAF, which appear to occur in mutually exclusive sets of tumours and lead to constitutively active MEK–ERK signalling." (PMID 22536322, 2012).
melanoma (continued). "In both NSCLC and melanoma clinical benefit is not obtained in patients without these genomic changes, and moreover in the case of vemurafenib the therapy may theoretically induce proliferation of cases of melanoma without BRAF mutations." (PMID 25562798, 2012). "In addition, our analysis of a set of matched primary and metastatic tumors from individual patients further suggests that BRAF mutations may not be required for development of metastasis in BRAFV600E-mutant primary melanomas." (PMID 22235286, 2012). "Furthermore, many of the studies were performed on different established melanoma cell lines which have various additional mutations besides those in BRAF that may or may not be relevant for actual melanomas present in patients." (PMID 23085539, 2012). "Thus, mutations in BRAF do not appear to be an initiating event for all cells in a given nevus or melanoma, even those neoplasms in which the mutation can be detected, as it may be present in only a subset of tumor cells." (PMID 22235286, 2012). "In melanoma cells, mTORC2 purified from A375(BRAFV600E) also showed lower enzyme activity compared to that purified from CHL1(wild-type BRAF)." (PMID 22880048, 2012). "Conversely, RAF inhibitors paradoxically enhance ERK activation and proliferation in BRAF-wildtype, RAS-mutant melanoma (and normal) cells through a mechanism that involves the interaction of these drugs with RAF dimers." (PMID 23039341, 2012). "An anti-CTLA-4 monoclonal antibody (ipilimumab) and a BRAF inhibitor (vemurafenib) were approved in 2011 by FDA to treat advanced melanoma, which herald a new era of targeted therapeutics for melanoma." (PMID 23166634, 2012). "Taken together, our findings suggest that in a subset of BRAFV600E melanoma cells, BRAFV600E negatively regulates AKT pathway in a rictor-dependent, MEK/ERK and BRAF kinase-independent manner." (PMID 22880048, 2012). "Clinical trials are currently ongoing to validate the combination of BRAF and MEK inhibitors in BRAF V600E mutant melanoma, with trials on the combination of BRAF with AKT inhibitors due to commence in the near future." (PMID 21505227, 2011). "In the development of melanoma, however, an optimized level of MITF as an oncogene for proliferation and survival of tumor cells needs to be maintained by BRAF." (PMID 22007305, 2011). "Moreover, a mouse model of melanocytic nevus and melanoma, which is driven by the inducible expression of BRAFV600E in melanocytes, has been developed recently, providing further evidence that the acquisition of a BRAF mutation can be a founder event in melanocyte transformation." (PMID 21224857, 2011). "Such mutations have been documented in all subtypes of melanoma, including cutaneous (50–60% BRAF, 15% NRAS and 17% CKIT chronic sun damage), mucosal (11% BRAF, 5% NRAS and 21% CKIT) and uveal (50% GNAQ) melanomas." (PMID 21139585, 2011). "Accordingly, RND3 expression and suppressed RHOA signaling appear to be important for normal melanoma cell movement, whereas RND3 downregulation and enhanced RHOA signaling are critical in BRAF-inhibitor treated cells." (PMID 21917148, 2011). "Results of an ongoing melanoma phase-I/II trial (RAF265-MEL01; wt BRAF and BRAF mutant patients included) are awaited." (PMID 21139585, 2011). "GSK 2118436 is an ATP competitive, reversible inhibitor of the mutant BRAFV600E/K/D (IC50 0.5, 0.6, 1.9 nM, respectively), wt BRAF (IC50 12 nM) and CRAF (IC50 5 nM) kinases with promising preclinical efficacy data in melanoma." (PMID 21139585, 2011). "The cross-resistance between the BRAF and MEK inhibitors is rather surprising given the exquisite dependence that BRAFV600E mutant melanomas have demonstrated on the MAPK pathway." (PMID 22194965, 2011). "Thus, it may be surprising that melanoma cells acquiring activating BRAF mutations constitute only a minor subpopulation of primary tumours and do not outgrow BRAF-wild-type cells." (PMID 21224857, 2011).
melanoma (continued). "Pleasingly, this compound was found to inhibit isolated full length V600EBRAF at low micromolar concentrations (IC50 BRAF = 1.6 μM) and also to inhibit V600EBRAF signalling in melanoma cells (GI50 SRB = 7.4 μM)." (PMID 20667740, 2010). "Similar to the melanoma model, in MSI CRC cells, it was shown that BRAF V600E–ERK signalling is important in the regulation of proliferation through the p27Kip1 and cyclin D1 proteins." (PMID 20485284, 2010). "We have gone on to show that as a consequence of ERK being constitutively activated in melanoma cell lines expressing oncogenic BRAF, MITF protein levels are lower in mutant BRAF melanoma cells than in melanocytes." (PMID 18628967, 2008). "Our data suggest that oncogenic BRAF plays a critical role in regulating MITF expression to ensure that its protein levels are compatible with proliferation and survival of melanoma cells." (PMID 18628967, 2008). "Previous studies have shown that V600EBRAF stimulates melanoma cell proliferation and here we show that MITF is required for proliferation in these cells, because MITF depletion blocks DNA synthesis in BRAF mutant melanoma cells." (PMID 18628967, 2008). "Through these opposing mechanisms, oncogenic BRAF executes exquisite control over MITF expression, ensuring that the protein levels are permissive for melanoma cell survival and proliferation." (PMID 18628967, 2008). "Inhibitors which target the BRAF/MAP kinase pathway are currently under intense preclinical and clinical investigation in melanoma." (PMID 17245336, 2007). "In the vitro, amuvatinib inhibited the growth of NRAS‐mutant melanoma cell by inducing G2/M‐phase cell cycle arrest and apoptosis, but not BRAF‐mutant melanoma cell lines." (PMID 41492362, 2026). "Biopsy revealed an ulcerated malignant melanoma, at least stage IIB, BRAF V600 wild type." (PMID 41450449, 2026). "The mechanism involving combined BRAF inhibition and WNT/β‐catenin activation involved AXIN1 degradation and GSK3β inhibition, while hyperactivation of the MAPK/ERK pathway stabilized AXIN1 and consequently inhibited WNT signaling in melanoma." (PMID 41492362, 2026). "While some authors suggest that BRAF or NRAS mutations are obligatory initiating events, others have identified melanomas lacking these mutations yet harboring alterations in NF1 or other MAPK regulators." (PMID 41516405, 2026). "Prior studies in patients with BRAF‐mutant melanoma have shown increased density of tumor infiltrating lymphocytes (TIL) after 2 weeks of BRAF (BRAFi) ± MEK inhibition (MEKi), but did not characterize the functional state or clonal diversity of TIL over time." (PMID 41514118, 2026). "However, the signaling switch from BRAF to CRAF and RAF dimerization in RAS‐mutant melanoma has been identified as potential mechanisms of insensitivity for BRAF inhibitors." (PMID 41492362, 2026). "A study on melanoma cells confirmed that DNL depends on the proteolytic activation of SREBP-1 and demonstrated that this process is a key mediator of the oncogenic effects of the BRAF gene, contributing to therapy resistance." (PMID 41596686, 2026). "In NRAS mutation melanoma cells, activation of the MAPK is achieved through the activation of CRAF, rather than BRAF in normal melanocytes." (PMID 41492362, 2026). "The combination of 2‐deoxy‐d‐glucose (glycolysis inhibitors) and sorafenib (multikinase TKI, which inhibits CRAF, BRAF, VEGFR‐2, VEGFR‐3, PDGFR‐β, Flt3, c‐Kit, and p38α67) significantly suppresses the tumor growth of patient‐derived xenografts of NRASQ61 melanoma." (PMID 41492362, 2026). "Uveal melanoma is an uncommon and special subtype of melanoma with a unique mutation landscape, lacking NRAS, BRAF, and NF1 mutation." (PMID 41492362, 2026). "Response to target therapy was lower, albeit not significantly, in rare BRAF mutant melanomas compared to V600E/K (48% vs. 66%, p > 0.05)." (PMID 42003243, 2026).
melanoma (continued). "In this prospective PMS study of encorafenib plus binimetinib combination therapy in Japanese patients with BRAF-mutant unresectable malignant melanoma, no new safety concerns were reported when compared with results from the global phase III, COLUMBUS trial." (PMID 39918770, 2025). "However, NRAS-mutant melanomas exhibit normal PTEN levels, suggesting BRAF-mutant and NRAS-mutant tumors differ in their mechanisms of progression towards BMs." (PMID 40076927, 2025). "Using naïve and resistant mouse YUMMER melanoma cells, we studied the effect of the BRAF inhibitor Vem with or without CCG-257081 on real-time growth and apoptosis (activation of caspase, Propidium iodide (PI) staining, and PARP cleavage)." (PMID 39917624, 2025). "The top 10 productive journals in BRAF and MEK inhibitor resistance research in melanoma." (PMID 39897423, 2025). "Currently, three different BRAF/MEKi combinations have demonstrated an ORR of 64–69% and a 5-year OS rate of approximately 34% in their pivotal trials, all of which have been approved by the FDA and EMA in the setting of advanced melanoma." (PMID 39859576, 2025). "In cancers where mutations in the MAPK pathway confer resistance to BRAF inhibitors, such as melanoma, these exosome-encapsulated siRNAs can silence MEK or ERK, thereby inhibiting compensatory survival signaling and restoring the efficacy of BRAF-targeted therapies." (PMID 40843170, 2025). "Our previous study uncovered a growth-promoting role of proinflammatory cytokines in melanoma cells through JNK-ITCH-mediated non-proteolytic ubiquitination of the BRAF kinase." (PMID 40462232, 2025). "The top 10 most productive countries in BRAF and MEK inhibitor resistance research in melanoma." (PMID 39897423, 2025). "BRAF/MEK inhibitors have limited intracranial efficacy and are theoretically considered unable to effectively cross the blood–brain barrier, yet clinical data have demonstrated efficacy in melanoma brain metastases." (PMID 40332392, 2025). "However, the use of systemic therapy including immunotherapy (immune checkpoint inhibitors) and targeted therapy (combination of BRAF/MEK inhibitors) improved the tumour response and survival in patients with melanoma brain metastases." (PMID 39752093, 2025). "A somewhat paradoxical link comes from melanoma patients placed on BRAF inhibitors, who subsequently develop cSCCs resulting from the superactivation of MAPK in skin epithelial cells that are wild type for BRAF." (PMID 39455281, 2025). "In melanoma, SOX10 is phosphorylated and regulated by ERK-mediated sumoylation at Lys55, a modification crucial for its transcriptional activity and target gene selection, particularly in BRAF-mutant melanoma." (PMID 40872623, 2025). "BRAF and NRAS mutations were found in 20% of spitzoid melanomas in one study, which was lower than the 61% in nonspitzoid melanoma." (PMID 39415471, 2025). "Genomic, non-genomic, and immune alterations contribute to melanoma resistance to BRAF and MEK inhibitors." (PMID 41550951, 2025). "Moreover, there is emerging interest in the use of neoadjuvant BRAF and MEK inhibitors to improve treatment outcomes for melanoma patients." (PMID 40861441, 2025). "Importantly, all of the top 10 co-cited journals are categorized in the Q1 quartile, underscoring their central role in shaping the research landscape of BRAF and MEK inhibitor resistance in melanoma." (PMID 39897423, 2025). "However, the emergence of resistance to BRAF and MEK inhibitor-based melanoma therapy, as well as the reduced sensitivity of other BRAF-mutant cancers such as CRC, poses a considerable clinical problem." (PMID 39935431, 2025). "Further, this combination therapy is contraindicated in patients with BRAF wild-type melanoma, as there have been no recorded benefits." (PMID 40004731, 2025).
melanoma (continued). "Here, we isolate distinct melanoma states with unique phenotypes: a MYC-driven state, essential for tumor initiation yet sensitive to BRAF inhibition, and a dedifferentiated, invasive BRN2-high state enriched in therapy-resistant cells but not directly tumorigenic." (PMID 41405996, 2025). "Nelfinavir, an HIV-1 protease inhibitor, is an essential salvage therapy for treating non-mutational drug tolerance developed in BRAF- and NRAS-mutant melanomas during the therapy phase due to a PAX-3-mediated increased expression of the MITF gene." (PMID 41516092, 2025). "Since Src kinases function together with FAK, we hypothesized that co-targeting BRAF/MEK and FAK with avutometinib (RAF/MEK clamp) plus defactinib (FAKi) would show activity against Rac1-driven drug-resistant melanoma cells." (PMID 41109929, 2025). "Inulin shows significant promise in the context of melanoma by enriching antitumor microbial populations and enhancing the therapeutic efficacy of MEK inhibitors, particularly in BRAF-mutant melanoma, a subtype characterized by aggressive cell growth and poor prognosis." (PMID 41424605, 2025). "The top 10 co-cited journals in BRAF and MEK inhibitor resistance research in melanoma." (PMID 39897423, 2025). "Therefore, we conducted a systematic review and meta-analysis to compare the efficacy of these two adjuvant treatment modalities in BRAF-mutant stage III and resected stage IV melanoma." (PMID 40758471, 2025). "Immune checkpoint inhibitors (ICIs) targeting PD-1 and CTLA-4, as well as targeted therapies such as BRAF/MEK inhibitors, have transformed the landscape of advanced or unresectable melanoma wherein 5-year survival rates of 30%-50% have been achieved in phase III clinical trials." (PMID 40857557, 2025). "In our cohort of 49 melanoma patients treated with BRAF/MEK inhibitors, antibiotic use did not worsen outcomes (objective response rate, progression-free survival, and overall survival)." (PMID 41294692, 2025). "Wild-type BRAF gene harbouring melanoma cells exhibited neither the characteristics of senescent cells nor changes in adhesion levels." (PMID 40636307, 2025). "Among these, the development of immunotherapies (e.g. interferon (IFN) alpha-2b, interleukin (IL)-2, and PD-1 inhibitors) and targeted therapies (e.g. BRAF/MEK-targeted therapy) has greatly improved progression-free survival and melanoma-specific survival of patients with advanced melanoma." (PMID 40896437, 2025). "Another phase II trial found that no BRAF-wild type melanoma patients achieved a noticeable objective response when treated with the combined uprosertib-trametinib regimen (NCT01941927)." (PMID 40399946, 2025). "In turn, DSF/Cu did not reduce the number of viable BRAFV600E and KRASG12V melanoma cells or only moderately induced apoptosis in wild-type BRAF melanoma cells." (PMID 39970778, 2025). "HDAC10 maintained BRAF inhibitor resistance and proliferation of BRAFV600E A375 and WM793 melanoma cells by suppressing the glycoprotein SPARC (secreted protein acidic and rich in cysteine) via regulation of histone H3 acetylation in the SPARC gene regulatory elements together with the HAT p300." (PMID 39935431, 2025). "Rapid EGFR feedback activation has been established as one of the mechanisms of intrinsic resistance to BRAFi in BRAFV600E CRC, which does not occur in BRAFV600E melanoma and explains the sensitivity of the latest to BRAF inhibitors in the clinic." (PMID 40481178, 2025). "The combinations of atezolizumab (anti-PD-L1) with sunitinib (VEGFR inhibitor), and pembrolizumab (anti-PD1) with dabrafenib (BRAF inhibitor) and trametinib (MEK inhibitor) are under phase 3 and phase 2 clinical trials in metastatic RCC and BRAF-mutant melanoma, respectively." (PMID 40282457, 2025). "Thus, the combination of BRAF and MEK inhibitors has become the standard treatment for advanced melanoma." (PMID 41367868, 2025).